SOD1 (superoxide dismutase 1)
Diseases named in the same sentence as SOD1 in open-access papers (continued):
Sharing a sentence is not in itself a finding about the gene and the disease.
breast carcinoma (continued). "For example, in the colorectal cancer cell line LS-180, SOD activity was found to be upregulated, while in the breast cancer cell line SKBR3, SOD1 was found to be downregulated and SOD2 upregulated." (PMID 33086722, 2020). "CCS, a co-enzyme of SOD1, is a critical component of the oxidation–reduction system in cancer, and its differential expression in different types of breast cancer suggests a relationship between CCS and cancer cell growth and migration." (PMID 31024318, 2019). "The expression of SOD1, the most abundant SOD protein in cytoplasm, is increased in mammary carcinomas and lung carcinomas." (PMID 31658599, 2019). "Increased activity of SOD1 in breast cancer cells, compared with normal mammary cells, can have its contribution in the increased resistance of breast cancer cells to oxidative stress." (PMID 30347787, 2018). "Previous studies have shown that during transformation, breast cancer cells predominately expressing SOD2 to expressing SOD1 as the primary superoxide dismutase isoform." (PMID 29891006, 2018). "SOD1 is overexpressed in the MCF-7 cell compared to normal cells, and shSOD1RNA treatment resulted in significant reduction in viability of the MCF-7 cell, indicating endogenous SOD1 is critical for maintaining breast cancer cell physiological function." (PMID 28280522, 2017). "To confirm the role of SOD1 in the diminution of DNA-PKcs expression after exposure to NSC, we addressed MDA MB468 breast cancer cells, in which SOD1 was the knockdown with siRNA." (PMID 27187356, 2016). "Yet, SOD1 has also a role in breast cancer and an ability to augment estrogen-responsive gene expression." (PMID 26493371, 2015). "We also reported the same inverse correlation between SIRT3 and SOD1 using immunohistochemistry on a tissue microarray of primary breast cancers." (PMID 24955214, 2014). "Adding to the importance of SOD1 in the mitochondria is a recent study from the Haigis' group showing that SIRT3 is either completely lost or reduced in 87% of breast cancers." (PMID 24955214, 2014). "We found that, while the SOD1 protein was undetectable in the mammary ducts of wild type females, high levels of SOD1 protein was detected in all three mammary tumor models." (PMID 24955214, 2014). "We previously demonstrated that increased SOD1 protects MCF-7 breast cancer cells from oxidative stress and now show that SOD1 expression is increased in human breast cancer tissue." (PMID 20064251, 2010). "Additionally, exosomal Survivin from breast cancer cells transforms fibroblasts into CAFs by upregulating superoxide dismutase 1 (SOD1), contributing to tumor growth." (PMID 40344389, 2025). "Meanwhile, the opposite correlations between YWHAE and YWHAZ with SOD1 from the breast cancer proteome data imply that these PPIs might drive different metabolic impacts in breast cancer development." (PMID 36834640, 2023). "Increased activity of SOD1 in breast cancer cells may contribute to the increased resistance of breast cancer cells to oxidative stress." (PMID 36985725, 2023). "SOD1 is overexpressed in most malignant breast cancer cells (e.g., MCF-7)." (PMID 36985725, 2023). "Another samll molecular LCS-1 (lung cancer screen 1, 4,5-Dichloro-2-(3-methylphenyl)-3(2H)-pyridazinone) is screened as an inhibitor of SOD1 and inhibits the growth of lung adenocarcinoma cell lines, and has been reported to induce death of colorectal cancer cells and breast cancer cells." (PMID 35978820, 2022). "Chebulinic acid (CA), a polyphenol derived from the fruits of various medicinal plants, downregulates the expression of SOD1, reduces its enzyme activity, elicits cell oxidative stress, inhibits cell proliferation and promotes cell apoptosis in breast cancer cells." (PMID 35978820, 2022). "Moreover, there is a switch from SOD2 to SOD1 during the transformation process in breast cancers, and SOD2 is downregulated in malignant breast cancer cells compared to their normal cell counterparts." (PMID 36009568, 2022).
breast carcinoma (continued). "SOD1-overexpressing fibroblasts promote the proliferation and metastasis of breast cancer." (PMID 34853307, 2021). "SOD1 levels are elevated in all three breast cancer cell lines versus fibroblast." (PMID 33669867, 2021). "Furthermore, the activity of SOD2 was decreased to 87% of breast cancer cases, whereas the levels of SOD1 and ROS were upregulated." (PMID 30279365, 2018). "SOD1 is overexpressed in malignant breast cancer cells (MCF-7)." (PMID 30347787, 2018). "In fact previous studies suggested that SOD1 might be of critical importance for the maintenance of the integrity of the organelle in breast cancer cells." (PMID 25996379, 2015). "In addition, the analysis of SOD1 in human primary breast cancers revealed that SOD1 accumulates not only in the cytoplasm but also in the nucleus of cancer cells." (PMID 24955214, 2014). "Therefore, our data indicates that the overexpression of SOD1 is a frequent occurrence in breast cancer." (PMID 24955214, 2014). "Interestingly, the level of SOD1 was considerably increased in both breast cancer cell lines, HCC1937 and MCF-7." (PMID 17192190, 2006). "Moreover, we found that Asc/TETA treatment also leads to a downregulation of SOD1 in MCF-7 cells, which is in accordance with the SOD1 shRNA experiment result, indicating the anti-breast cancer effects of Asc/TETA combination are partially mediated by the inhibition of SOD1." (PMID 28280522, 2017). "In addition, to further study whether the disturbed expression pattern of SOD1 and CAT in breast cancer cell is related with cell viability, SOD1 and CAT were knocked down by shRNA, respectively." (PMID 28280522, 2017). "Our laboratory identified oxidative stress (SOD1, Ape1/Ref-1, Trx, TrxR and PDI) and DNA repair (NM23-H1, MPG and Ape1/Ref-1) proteins associated with the DNA-bound ERα and showed that each of these proteins influences estrogen-responsive gene expression in MCF-7 human breast cancer cells." (PMID 20064251, 2010). "Therefore, targeting SOD1 may be a potential breast cancer treatment strategy." (PMID 38516703, 2024). "TPT-NCSe (500 nM) decreases SOD1 mRNA, increases SOD2 mRNA in MCF-7 breast cancer cells, and increases SOD2 mRNA in MDA-MB-231 cells." (PMID 38227157, 2024). "To find co-function or regulatory relationships for the putative PPIs between SOD1 and YWHAE or YWHAZ, we used a breast cancer quantitative proteome database to analyze latent correlations of their protein expression profiles." (PMID 36834640, 2023). "AR12 and the breast cancer drug neratinib (NER) rapidly reduced expression of Tau, amyloid precursor protein (APP), superoxide dismutase 1 (SOD1) and TAR DNA-binding protein 43 (TDP-43)." (PMID 36227739, 2022). "In breast cancer cells, SOD2 to SOD1 switch is found, resulting in the SOD2 down-regulation, and SOD1 upregulation, and SOD1 functions to maintain the integrity of the organelle." (PMID 35978820, 2022). "Since either PHA treatment or Baf A1/PHA cotreatments induced ROS, the effects of autophagy in antioxidant gene expressions such as SOD1, NFE2L2, TXN, and GSR in breast cancer cells were assessed by real-time PCR." (PMID 35883843, 2022). "Last, we analyzed the expression of novel breast cancer targets MCAM/CD146 and SOD1 in the cell lines." (PMID 26968831, 2016). "To further test this possibility, we analyzed the level of SOD1 in MMTV-Wnt, MMTV-erbB2 and MMTV-Myc mouse models of breast cancer." (PMID 24955214, 2014). "In general, more aggressive breast cancers (MDA-MB-231, SUM159PT, BCCL2, BCCL3) had lower levels of TMX1 and SOD1 relative to the luminal MCF-7 cells, and showed up-regulated expression of TMX3, Foxo1, GSS and SOD2." (PMID 22479642, 2012). "We have now shown that SOD1, Ape1/Ref-1, Trx, PDI and NM23-H1 are overexpressed and that the cellular localization of Ape1/Ref-1, Trx and PDI is altered in human breast cancer tissues." (PMID 20064251, 2010).
breast carcinoma (continued). "We have shown that SOD1, Ape1/Ref-1, Trx, PDI and NM23-H1 are overexpressed, and that the cellular localization of Ape1/Ref-1, Trx, and PDI is altered in human breast cancer tissue." (PMID 20064251, 2010). "SOD1 has been associated with tumor formation, TTF1 is also thought to be a negative prognostic factor in breast cancer, and FN14 has been associated with metastasis." (PMID 41149583, 2025). "In addition, breast cancer vesicular proteins such as survivin and ITGB4 converted NFs into myofibroblasts by increasing superoxide dismutase 1 (SOD1) and lactate in CAFs in a BNIP3L-dependent manner." (PMID 36612080, 2022). "Furthermore, the expression ratio of SOD1/SOD2 seems to be a switch and plays an essential physiological role in breast cancer cells." (PMID 30279365, 2018). "Following the finding that SIRT3 is decreased in 87% of breast cancer, we hypothesized that decreased expression of SIRT3 may be counterbalanced by an up-regulation of SOD1." (PMID 24955214, 2014). "Therefore, the switch mechanism of SOD1 to SOD2 may play a significant role in cellular physiology, such as invasion or proliferation of breast cancer cells." (PMID 30279365, 2018). "Our studies suggest that oxidative stress proteins (SOD1, Ape1/Ref-1, Trx, and PDI) and the DNA repair protein Ape1/Ref-1 not only protect normal cells from the damaging effects of ROS, but also promote survival of mammary tumor cells and foster tumor progression." (PMID 20064251, 2010). "Using a proteomic approach, we could show that several antioxidant proteins, for example, SOD1, PRDX2, and PARK7, were downregulated in the normo-sensitive patients and some antioxidant proteins, for example, BLVRB and PRDX2, were upregulated in the radiosensitive breast cancer patients." (PMID 29951164, 2018). "Moreover, SOD1 and N-acetyl-L-cysteine failed to improve MCF-7 cells viability in the presence of Asc/TETA, while catalase significantly inhibited the cytotoxicity of Asc/TETA to breast cancer cells, strongly suggesting that the selective cytotoxicity of Asc/TETA to cancer cells is H2O2-dependent." (PMID 28280522, 2017).
Cognitive impairment (109 papers, 2011 to 2026). Abnormal cognition is characterized by deficits in thinking, reasoning, or remembering. "In contrast to fALS associated with variants in e.g. C9ORF72, FUS, or TARDBP, there is hardly any cognitive impairment in SOD1-associated ALS70." (PMID 39366938, 2024). "Early cognitive impairment is extremely rare in SOD1-mutation carriers, and it is mainly reported in the late stages of the disease." (PMID 37265463, 2023). "The increase in CAT and SOD1 in the head is particularly important because neural tissues are highly sensitive to oxidative stress, and reduced antioxidant defense has been associated with cognitive impairments in bees exposed to pesticides." (PMID 41200016, 2025). "The results indicated that FH had protective effect against cognitive deficits induced by D-galactose through raising the protein expression of SOD1 and decreased genetic expression of IL-6 and AGE." (PMID 39446794, 2024). "This individual had a typical age of onset and relatively slow progression, perhaps in-keeping with a SOD1 phenotype, but had cognitive impairment in line with C9orf72 phenotype." (PMID 38852112, 2024). "Trans-cinnamaldehyde was proven useful to upregulating hippocampal SOD1 in mice with experimental cognitive impairment." (PMID 39061948, 2024). "The individual with both the C9orf72 expansion and SOD1 p(.Ile114Thr) variant was a male who had lower limb-onset ALS age 68 and who developed cognitive impairment as assessed by ECAS." (PMID 38852112, 2024). "Clinical phenotype in SOD1-related ALS (SOD1-ALS) is heterogenous, but it is frequently associated with the spinal onset and lower limb involvement, rare cognitive impairment, and slow progression." (PMID 37265463, 2023). "It is seen, with the exception of cases resulting from SOD1 mutations, in most post-mortem cases of FTD and ALS, and correlates well with synaptic pathology and cognitive deficits." (PMID 29115989, 2017). "The incidence of overt cognitive impairment in SOD1 ALS is also markedly lower." (PMID 41042072, 2025). "ECAS scores of SOD1 carriers were reflective of the population as a whole; patients with SOD1 mutations tend not to have significant cognitive impairment and so this was anticipated." (PMID 38852112, 2024). "In regard to the clinical features, cognitive impairment and bulbar onset was not common in Chinese patients with SOD1 mutations, which is consistent with previous reports." (PMID 31788332, 2019). "Although the exact mechanisms responsible for this effect are unclear, we can postulate that chronic treatment with α5IA could alleviate cognitive deficits at least partly through the normalization of Sod1 expression in the hippocampus." (PMID 22028705, 2011). "Emotional lability is elevated in both SOD1 and sporadic ALS (SALS) patients relative to controls, suggesting that emotional changes can occur independently of cognitive impairment in ALS." (PMID 40649976, 2025). "Indeed, it has been shown to improve cognitive deficits, suppress vascular aging and inflammation in elderly mice, and attenuate neuronal aging both in vitro and in vivo by downregulating the expression of p16 and p21 and upregulating antioxidant enzymes, including SOD1, CAT and GPx." (PMID 35883714, 2022). "Overall, SOD1 typically confers more LMN than UMN involvement, and cognitive impairment is not generally reported in SOD1 disease." (PMID 35273561, 2022). "The neuropentraxins are candidate markers of synaptic dysfunction in cognitive disorders, and even if an interaction with SOD1 has not been described yet, they might also reflect a beneficial effect on synaptic homeostasis upon tofersen exposure." (PMID 40781905, 2025). "Although ALS patients with SOD1 mutation do not typically show prominent cognitive deficits, cognitive deficits are a prominent feature in some ALS patients, and pyramidal neurons in the MPFC, a key cortical area for cognitive function, are altered in SOD1 mutant mice at P60." (PMID 27488828, 2016).
Cognitive impairment (continued). "However, Rembach (2013) has suggested the possibility of decreased non-CP copper levels-copper that is not bound to ceruloplasmin in mild cognitive impairment (MCI) and AD, which leads to a decline of copper-dependent biochemical activities in AD, such as reducing SOD1 activity of erythrocytes." (PMID 33081348, 2020).
Insulin resistance (100 papers, 2013 to 2026). Increased resistance towards insulin, that is, diminished effectiveness of insulin in reducing blood glucose levels. "Insulin resistance in the group of women with PCOS caused a further SOD1 activity decrease, while Cu concentration and the value of Cu/Zn was increased when compared to women with normal insulin levels." (PMID 35566673, 2022). "In addition to previous reports of the association of an imbalance in Zn and Cu levels with increased oxidative stress and inflammation, which impair insulin secretion and action, Zn deficiency may lower SOD1 activity in pancreatic islets, which has been shown to increase insulin resistance." (PMID 27895622, 2016). "A period of 12 weeks on a hypocaloric diet with 30 mg per day of elemental zinc supplementation, at the endpoint, resulted in a decrease in insulin resistance and improvement of the insulin serum superoxide dismutase 1 and malondialdehyde levels in overweight NAFLD-diagnosed patients." (PMID 36902639, 2023). "Naringin not only had improved insulin resistance and increased the gene expression of the antioxidant enzymes (SOD1 and CAT), mTOR, and PGC-1α, but the expressions of IRS-1 and GLUT4 proteins were also increased, which led to increases in the glucose uptake and the glycogen levels." (PMID 36235772, 2022). "Interestingly, we demonstrated that naringin can reduced insulin resistance and increase the mRNA expressions of SOD1, CAT, mTOR, and PGC-1α, while showing significantly decreased expressions of Atrogin-1 and MuRF-1 mRNA." (PMID 36235772, 2022). "In addition, Rha treatment modulated insulin resistance and increased gene expression of antioxidant enzymes (Cat, Sod2, Gpx3, Mgst1, Prdx3, Gsta4, Gsr, and Sod1) in the ovaries of the PCOS rats." (PMID 35663203, 2022). "Meanwhile, increased insulin-stimulated SOD1 expression suggests increased O2• − dismutation capacity, which may integrate with the PRX2 and GPx1 responses and counteract the chronic oxidative stress associated with insulin resistance." (PMID 37812879, 2023). "WT showed insulin resistance and elevated blood glucose in HFHSD, while SOD1−/− showed decreased insulin secretion and elevated blood glucose." (PMID 35883894, 2022). "In the present study, insulin resistance increased with increasing O2·− in WT with HFHSD, while in SOD1−/− with HFHSD, insulin secretion decreased and insulin resistance instead improved." (PMID 35883894, 2022). "The product of blood glucose and serum insulin levels (HOMA-IR equivalent) indicates insulin resistance, and this index was elevated in WT given HFHSD; however, it was lower in SOD1−/− given HFHSD." (PMID 35883894, 2022).
type 2 diabetes (92 papers, 2004 to 2026). "We also identified seven genes (Sardh, Slc39a7, Pfn1, Arg1, Cth, Sod1 and P4hb) in the liver and one gene (Fabp4) in the adipose tissue that may be associated with type 2 diabetes in gerbils." (PMID 29394254, 2018). "In addition, GLP-1R agonist exendin-4 has been shown to increase antioxidants (SOD-1 and glutathione peroxidase) to improve myocardial oxidative stress and ameliorates cardiac dysfunction in type 2 diabetes." (PMID 40232847, 2025). "In type II diabetes mellitus patients, SOD-1 activity was found to be altered." (PMID 34250558, 2022). "In the present study, we found that type 2 diabetes significantly down-regulated the expression of renal Nrf-2 and the downstream targets SOD-1, HO-1 and NQO-1, which were remarkably reversed by exposure to LDR, especially at 50 or 75 mGy for both 4 and 8 weeks." (PMID 24651118, 2014). "Expression of SOD1 did not change with training in men with type 2 diabetes, whereas SOD2 increased, suggesting a training‐induced enhancement in mitochondrial antioxidant protection." (PMID 33426802, 2021). "Specifically, protein levels of SOD1 and ETC complex V were lower in men with type 2 diabetes." (PMID 33426802, 2021). "That expression of muscle SOD1, that is, the cytosolic isoform of SOD, but not SOD2, that is, the mitochondrial isoform of SOD, was lower in the men with type 2 diabetes may suggest that type 2 diabetes is associated with blunted cytosolic antioxidant protection." (PMID 33426802, 2021).